BDNF (brain derived neurotrophic factor)
Diseases named in the same sentence as BDNF in open-access papers (continued):
Sharing a sentence is not in itself a finding about the gene and the disease.
psychological distress (16 papers, 2015 to 2026). "Although peripheral BDNF levels play a critical role in understanding the biological mechanisms associated with psychological distress, research has been constrained by the reliance on blood samples." (PMID 37822121, 2023). "We suggest that attenuated cortisol levels may act as the driving force to downregulate BDNF, increasing cardiometabolic risk and reducing coronary perfusion during psychological distress." (PMID 27966001, 2016). "Our findings support a theory that two direct paths to BDNF involve diet and psychological distress, while sleep is involved through an indirect pathophysiological pathway." (PMID 34895362, 2021). "This larger‐than‐expected difference could contribute to the higher degree of psychological distress in AYAC than HC, which has been linked with lower BDNF levels." (PMID 36221816, 2023). "However, no studies have investigated the potential of salivary mature BDNF (mBDNF) level as a noninvasive biomarker for psychological distress." (PMID 37822121, 2023). "The lack of similar association in the patient group, which had higher levels of psychological distress indicate that the relation between BDNF and psychological distress may be more complex." (PMID 32842964, 2020). "Although BDNF has been identified in saliva, including its expression in the human submandibular gland, the extent to which salivary mBDNF interacts with psychological distress in the healthy population, including healthcare workers, remains unclear." (PMID 37822121, 2023). "While evidence suggests that diet may directly impact on BDNF levels - a neurotrophic factor of which lower levels are associated with OCD, better sleep quality may improve resilience to psychological distress and emotion regulation which, in turn, may upregulate BDNF." (PMID 34895362, 2021). "Our open-label pilot study showed that supplementation with docosahexaenoic acid (DHA) increased serum brain-derived neurotrophic factor (BDNF) levels and that there might be an association between changes in serum BDNF levels and reduced psychological distress." (PMID 26151924, 2015). "BDNF further moderates stress responses by attenuating HPA-axis reactivity, promoting emotional resilience, and alleviating psychological distress." (PMID 41358241, 2025). "The level of antioxidant markers and brain-derived neurotrophic factor were altered in PINK1-KO-PBMCs and by psychological distress." (PMID 32555260, 2020). "However, psychological distress did not significantly affect the intracellular level of BDNF in PBMCs suggesting that oxidative stress induced by psychological distress causes differential effects on the level of BDNF in the brain and peripheral tissues." (PMID 32555260, 2020). "BDNF and NGF concentrations correlated to levels of psychological distress (p < 0.0005)." (PMID 32842964, 2020). "On the other hand, psychological distress did not alter BDNF level in both WT and PINK1-KO cells." (PMID 32555260, 2020). "Consequently, trends in BDNF levels, cognition, fatigue, and psychological distress may not accurately reflect the AYA cancer population." (PMID 37770565, 2023).
substance abuse (16 papers, 2008 to 2025). The use of a drug for a reason other than which it was intended or in a manner or in quantities other than directed. "In contrast, physical exercise not only addresses these limitations but also reverses physiological and neural damage caused by substance abuse and increases the release of brain-derived neurotrophic factor (BDNF), contributing to its antidepressant effects." (PMID 39555034, 2024). "The suggested importance of BDNF to drug abuse has prompted studies investigating human polymorphisms of the BDNF gene; however, currently only modest associations between BDNF gene variants and substance abusers have been identified." (PMID 25922574, 2008). "This study aimed to analyse the association of the rs6265 polymorphism of the BDNF gene in a group of patients addicted to psychoactive substances participating in addiction treatment for the first time, in a group of post-relapse psychoactive substance abusers and a control group." (PMID 38255861, 2024). "This study analyzed the association of the rs6265 polymorphism of the BDNF gene in a group of patients addicted to psychoactive substances who were participating in addiction treatment for the first time, in a group of post-relapse psychoactive substance abusers and in a control group." (PMID 38255861, 2024). "It is increasingly recognised that such activity-dependent remodelling is crucial for the transition from casual substance use to substance dependence, leading to the investigation of the role of BDNF in the actions of substance abusers." (PMID 38255861, 2024). "Current research has largely confirmed that exercise can modulate dopamine (DA) and endogenous opioid peptide (EOP) systemic disorders after substance abuse, increase the levels of oxytocin and brain-derived neurotrophic factor, and enhance the function of the neuroimmune system." (PMID 39705420, 2024). "This might indicate that BDNF could be a biomarker of both substance abuse and substance-related cognitive impairment, as our group has reported in previous studies." (PMID 36674698, 2023). "In this regard, since it is well-documented that an increase in BDNF content in the NAcc increases cocaine-seeking behavior and vulnerability to substance abuse, an increase in proBDNF in this brain area could have an opposite impact." (PMID 30890941, 2019). "BDNF and trkB−TK mRNA levels were generally not affected by gender, hemisphere, suicide, history of substance abuse or by smoking." (PMID 24802307, 2014).
viral infection (16 papers, 2016 to 2026). "The authors noted that M2 microglial state is responsible for mediating anti-inflammatory responses to damage caused by viral infection, but also that M2 microglial cells secrete BDNF, assisting in stimulating neural progenitor cell production and therefore promoting neurogenesis." (PMID 29681622, 2018). "The AAV2-DIO-BDNF-mCherry virus infection site is localized at 2.1 mm from bregma on the AP axis in the vlOFC, confirming that BDNF is overexpressed in the vlOFC to DLS circuit." (PMID 41207892, 2026). "Three weeks following viral infection enabling maximal BDNF expression, mice were subjected to 7 weeks of IA20%2BC or water only." (PMID 39868120, 2025). "In animal models, mechanoreceptors express TRPV1 de novo after allergen exposure and virus infection, possibly due to induction of the neurotrophin brain-derived neurotrophic factor (BDNF)." (PMID 37985513, 2023). "the participation of NGF and BDNF in viral infections, chronic lung inflammation, and tissue remodeling (fibrosis)-associated states; ii." (PMID 36579579, 2022). "As a practical example, Sindbis viral infection of hippocampal neurons has previously been used to enable cultured neurons to selectively express constructs containing either valine BDNF (valBDNF) or methionine BDNF (metBDNF), followed by GFP." (PMID 35090576, 2022). "Two of the most studied are nerve growth factor (NGF) and brain-derived neurotrophic factor (BDNF), which are released by inflammatory cells and by airway epithelium in the setting of allergen exposure, virus infection, and other insults." (PMID 34557110, 2021). "We were therefore particularly interested in whether viral infection leads to BDNF production in the airways." (PMID 27213574, 2016). "Therefore, the increased levels of NGF and BDNF might be viewed as an outcome of the immune response to viral infection." (PMID 36579579, 2022). "We found an inverse correlation between the protein levels of BDNF and KCC2 in mice hippocampus during the peak seizure activity period following viral infection." (PMID 35874836, 2022). "After virus infection, four groups of mice, the EGFP+STZ, BDNF+STZ, EGFP Control and BDNF Control groups, received STZ or vehicle treatment as indicated." (PMID 31165005, 2019).
WAGR syndrome (16 papers, 2008 to 2024). WAGR syndrome (Wilms tumor - aniridia - genitourinary anomalies - intellectual disability mental retardation) is a rare genetic disorder characterized by an unusual complex of congenital developmental abnormalities with intellectual disability, and an increased risk of developing Wilms tumor. "An additional study reported a BDNF haploinsufficiency in a cohort of patients with WAGR syndrome, a rare genetic disorder caused by contiguous gene deletions on chromosome 11p13 region of varying size." (PMID 34833132, 2021). "Eight probes were screened in the 11p13 region associated with WAGR syndrome, in BDNF (2 probes), PAX6 (3 probes), WT1 (2 probes) and HIPK3 (1 probe)." (PMID 18925931, 2008). "Since the BDNF gene is located in the chromosomal locus 11p14.1, approximately half of the patients with WAGR syndrome had a heterozygous BDNF deletion." (PMID 34833132, 2021). "Furthermore, individuals with WAGR syndrome and related BDNF haploinsufficiency exhibit childhood-onset obesity and lower BDNF serum levels." (PMID 38672441, 2024). "Deletion of BDNF gene was described in obese patients with WAGR syndrome." (PMID 25122490, 2014).
brain tumor (15 papers, 2019 to 2026). "We additionally confirmed increased expression of brain-derived neurotrophic factor (BDNF) precursor protein in the brain tumors of mice receiving combination therapy, compared with vehicle-treated controls." (PMID 37991020, 2023). "Brain-derived neurotrophic factor (BDNF) is commonly used as a neuroprotective agent to prevent neuronal death after brain injury or development of brain tumors." (PMID 36109754, 2022). "This was shown by its effectiveness to inhibit orthotopic brain tumors when drug was given orally and by induction of synthesis of BDNF as previously shown by us and others." (PMID 33013390, 2020). "BDNF levels were found to increase in the CSF of affected children, suggesting distinct correlations between neurotrophic factors and the biology of low‐grade astrocytomas and ependymomas in childhood brain neoplasms." (PMID 39789839, 2025). "Downregulation of BDNF may be a common feature not only in MB but among other brain tumor types." (PMID 32906676, 2020). "Paracrine signaling through soluble factors such as brain-derived neurotrophic factor (BDNF), 78 kDa glucose-regulated protein (GRP78), and neuroligin-3 (NLGN-3) is another route of communication in brain tumor networks." (PMID 36831383, 2023). "Similarly, the specific activation of neurotrophic factors, receptors TrkB and TrkC by their ligands neurotrophin 3 (NT3) and brain-derived neurotrophic factor (BDNF) via Akt and ERK pathways, promotes the survival of brain tumour-initiating cells." (PMID 41301734, 2025). "In contrast to subjective CRCI, we did not detect any significant association between BDNF Val66Met polymorphism and objective CRCI, a trend which is consistent with findings from our previous work as well as other studies in breast and brain tumor patients." (PMID 30382534, 2019).
dependence (15 papers, 2008 to 2025). "This is consistent with clinical studies showing higher relapse rates in Val/Val carriers compared to Met allele carriers and that BDNF Val/Val homozygosity confers genetic susceptibility towards substance dependence." (PMID 37372084, 2023). "Multiple lines of evidence have further linked alcohol preference and dependence with lower expression of BDNF in the amygdala and the prefrontal cortex." (PMID 32399021, 2020). "For example, BDNF (a ligand of TrkB) has been implicated in substance dependence as well as antinociception." (PMID 23840749, 2013). "Brain-derived neurotrophic factor (BDNF) has long been linked to neurodegenerative diseases and psychiatric disorders such as substance dependence." (PMID 36151087, 2022). "Brain-derived neurotrophic factor (BDNF) is characterized by a neurotrophin that exerts support of neuronal survival, differentiation, and connectivity which can have an impact on substance dependence." (PMID 28811779, 2017). "Based on their study, we deduced that striatal miR124a and BDNF signalling have crucial roles in alcohol consumption and dependence." (PMID 27767084, 2016). "Almost consistently, these studies revealed that polymorphisms in COMT, BDNF, and FKBP5 genes might interact with early life stress and cannabis abuse or dependence, influencing various outcomes of schizophrenia spectrum disorders and BD." (PMID 28822116, 2018).
manic episodes (15 papers, 2015 to 2024). "BDNF as a molecular marker has been robustly linked with bipolar episodes in patients, with low levels of BDNF associated with depressive and manic episodes, as well as their severity." (PMID 35546951, 2022). "BDNF levels were found to be moderately decreased in individuals with BD experiencing manic episodes and significantly decreased during depressive episodes." (PMID 37592949, 2023). "BDNF plays a pivotal role in the manifestation of psychosocial stress and recurrent manic episodes in BD." (PMID 33274124, 2020). "An increase in BDNF levels has revealed decreased depressive and manic episodes, suggesting the use of serum BDNF as a potential biomarker in BD." (PMID 33274124, 2020). "Regarding BDNF, the serum levels of this neurotrophin in BD patients are decreased in depressive and manic episodes, returning to normal levels in euthymia with a similar pattern of alteration in animal models of mania." (PMID 26075103, 2015). "On the other hand, research has indicated that the expression of the brain-derived neurotrophic factor (BDNF) gene is significantly decreased in patients during manic episodes and that the expression of this gene is negatively correlated with the severity of manic episodes." (PMID 38505796, 2024). "Of note, the upregulation of BDNF through exercise shares a similar pathway to that of antidepressants which could theoretically lead to exercise triggering potential manic episodes." (PMID 25788889, 2015). "In our research on adolescent patients, we did not notice differences in BDNF levels between depressive or hypomanic/manic episodes compared to the healthy controls." (PMID 34575175, 2021). "In addition, the same study found that peripheral BDNF levels increased after successful treatment of a manic episode but not of a depressive episode." (PMID 37592949, 2023). "In sharp contrast to the increased plasma BDNF levels found with treatment of a manic episode, no increase in peripheral BDNF levels were found after treatment of a depressive episode, regardless of whether it was plasma or serum, and regardless of the presence, or not, of response to treatment." (PMID 26621529, 2015).
nicotine dependence (15 papers, 2012 to 2025). Physical and psychological dependence on nicotine. "We assumed that BDNF Met allele carriers are more likely to continue smoking, as past studies have linked this gene to nicotine addiction." (PMID 38114721, 2023). "Our findings indicated reduced nicotine dependence among current smokers who carried the BDNF Met allele relative to those homozygous for the Val allele." (PMID 30815604, 2019). "Several studies have investigated the associations of BDNF Val66Met with smoking behavior and nicotine dependence." (PMID 30815604, 2019). "The present study thereby provides preliminary data suggesting potential associations of BDNF polymorphism with nicotine dependence and the age at smoking initiation due to an interacting 5-HTTLPR polymorphism in a small number of Japanese participants." (PMID 30815604, 2019). "The association between polymorphisms in the BDNF gene and nicotine dependence also has been described." (PMID 28724413, 2017). "Genome-wide linkage scans indicate that the region of chromosome 11p13 where the BDNF gene is located likely harbors susceptibility genes for nicotine dependence." (PMID 23285275, 2012). "The evidence suggests an association between allelic variants of BDNF and nicotine dependence in male European-American smokers." (PMID 23285275, 2012). "In the present study, we, therefore, investigated the hypothesis that BDNF Val66Met is associated with smoking cessation and initiation, nicotine dependence and the age of smoking initiation in Japanese participants." (PMID 30815604, 2019). "Accordingly, the BDNF Met allele may be associated with reduced nicotine dependence independently of 5-HTTLPR polymorphism." (PMID 30815604, 2019). "Recent studies demonstrate that brain-derived neurotrophic factor (BDNF) might be associated with nicotine addiction, and circulating BDNF is a biomarker of memory and general cognitive function." (PMID 30659208, 2019). "Association studies have also suggested that the BDNF gene might play a role in the susceptibility to nicotine dependence but results appear contradictory." (PMID 23285275, 2012). "Several recent studies have supported the hypothesis that brain-derived neurotrophic factor (BDNF), a member of the neurotrophic factor family, might be associated with nicotine addiction." (PMID 23285275, 2012). "Hence, given the underrepresentation of women in nicotine dependence research and the growing recognition of sex-specific influences on addiction, this study focuses on investigating the interplay between BDNF polymorphisms, personality traits and nicotine use in a female-only sample." (PMID 40806241, 2025). "Thus, studies are necessary to better define the role of BDNF Val66Met in nicotine dependence and whether harboring this polymorphism may have therapeutic implications." (PMID 23285275, 2012). "Our novel findings of dysregulated methylation patterns in exon IV of the BDNF gene further support the thesis that BDNF plays a role in nicotine dependence." (PMID 35836661, 2022). "In the context of nicotine dependence, several animal studies suggest that BDNF is functionally involved." (PMID 35836661, 2022). "We used the Fagerström test for nicotine dependence (FTND) to assess how BDNF promoter methylation and protein levels related to addiction severity." (PMID 35836661, 2022). "Previous studies showed that BDNF played an important role in nicotine addiction and eating disorders." (PMID 34525971, 2021). "Our study demonstrated an association between BDNF Val66Met and the HSI, a measure of the degree of nicotine dependence, in our participants." (PMID 30815604, 2019). "Further, smoking quantity, severity of nicotine dependence and smoking cessation affect BDNF expression levels." (PMID 28399944, 2017).